MSX2P1 (msh homeobox 2 pseudogene 1)
Synonyms: HSHPX5; HPX5; formerly MSX2P
Gene: Processed pseudogene on chromosome 17 (58,157,028 to 58,157,800, forward strand). Ensembl gene ENSG00000229590.
Diseases named in the same sentence as MSX2P1 in open-access papers:
MSX2P1 is named in the same sentence as 2 diseases in open-access papers, as found by Europe PMC text mining. Sharing a sentence is not in itself a finding about the gene and the disease. The quoted sentences say what the papers report.
psoriasis (6 papers, 2020 to 2024). An autoimmune condition characterized by red, well-delineated plaques with silvery scales that are usually on the extensor surfaces and scalp. "Given that S100A7 is tightly associated with keratinocyte hyperproliferation in psoriasis, MSX2P1–miR−6731-5p biological regulation is a potential novel therapeutic target for treating psoriasis." (PMID 37310201, 2023). "Several lncRNAs are upregulated in psoriasis, such as MSX2P1, XIST, FABP5P3, KLDHC7B-DT, or SPRR2C, whereas MEG3, GAS5, PRINS or NEAT1 are downregulated in psoriasis." (PMID 38256115, 2024). "Other upregulated lncRNA in psoriasis are MIR31HG, MSX2P1, XIST, FABP5P3, KLDHC7B-DT, or SPRR2C; whereas, MEG3, GAS5, PRINS or NEAT1 are downregulated in psoriasis." (PMID 37628670, 2023). "Other lncRNAs that have revealed roles in psoriasis include lncRNA RP6-65G23.1, lncRNA MSX2P (cytoplasmic lncRNA Msh homeobox 2 pseudogene 1), and lncRNA GAS5 (growth arrest specific 5)." (PMID 35559048, 2022). "While a number of lncRNAs such as MEG3, AL162231.4 and NONHSAT044111 have been down-regulated in the course of psoriasis, others including PRINS, MIR31HG, RP6‐65G23.1, MSX2P1, SLC6A14-1:1, NR_003062 have been up-regulated." (PMID 32695942, 2020).
tumor (1 paper, 2019). "Studies have revealed that AATBC, ADAMTSL4-AS1, EPB41L4A-AS1, MIA-RAB4B, MIR4697HG, GAS5, SNHG12, MSX2P1, and LINC00852 are related to tumorigenesis and tumor progression in multiple cancers, such as bladder, breast, colorectal, and ovarian." (PMID 31850068, 2019).